GSDMD (gasdermin D)
Diseases named in the same sentence as GSDMD in open-access papers (continued):
Sharing a sentence is not in itself a finding about the gene and the disease.
colitis (continued). "Our data suggest that decreased IL-1β is not important for GSDMD-mediated colitis promotion." (PMID 34721422, 2021). "The study proposes a physiological role for non-canonical inflammasome and GSDMD activation, limiting the severity of experimental DSS-colitis models by restricting cGAS-mediated inflammation in macrophages, independent of microbiota-associated changes or the production of antimicrobial peptides." (PMID 35712726, 2022).
breast cancer (51 papers, 2017 to 2026). A primary or metastatic malignant neoplasm involving the breast. "We found that, in breast cancer, high GSDMD mRNA expression was associated with a clear myeloid cell signature, characterized by a downregulation of markers associated with M2-type macrophages and a poor prognosis." (PMID 39224600, 2024). "To further investigate the role of GSDMD in anticancer immunity, we induced breast cancer and hepatoma tumors in GSDMD-deficient mice." (PMID 39224600, 2024). "To specifically examine the role of GSDMD expression by host cells in the antitumor immune response, we used two different tumor models, one for breast cancer and one for hepatoma in GSDMD-deficient mice." (PMID 39224600, 2024). "Using GSDMD-deficient mice, we found that growth of implanted breast cancer, known to be dependent on IL-1β, as well as of hepatoma tumors was independent of the expression of GSDMD in the tumor microenvironment." (PMID 39224600, 2024). "Docosahexaenoic acid (DHA) causes an increase in caspase-1 and GSDMD activity in breast cancer cells, triggering pyroptosis and inhibiting breast cancer growth." (PMID 37542283, 2023). "Several studies have found that the DHA can trigger caspase-1 and GSDMD activation to cause pyroptosis in breast cancer cells, and enhance the secretion of IL-1β." (PMID 32182796, 2020). "Since GSDMD is associated with better prognosis in this tumor type, these results suggest that in breast cancer, GSDMD may have other functions besides mediating the release of IL-1β." (PMID 39224600, 2024). "Interestingly, in an immunohistochemical study on breast cancer, upregulated GSDMD levels were found to have been associated with a lower historical grade and historical stage, indicating that GSDMD acts as a tumor-suppressor gene in breast cancer." (PMID 37511974, 2023). "Furthermore, high GSDMD expression has been linked to longer overall survival and less cancer cell invasion in breast cancer." (PMID 36120543, 2022). "detected the expression level of caspase-1, IL-1βand GSDMD, and they found that the expression of pyroptosis-related proteins were inversely correlated with the tumor grade, tumor size, clinical stage, death risk of breast cancer tissues." (PMID 34381721, 2021). "Our study reveals that OpA induces typical pyroptotic characteristics, including cell membrane rupture, cell swelling, the release of cytokines, and GSDMD cleavage in select breast cancer cells." (PMID 41596270, 2026). "In a representative HER2-positive breast cancer cell line, OpA induces GSDMD cleavage and cytokine release, evidence for pyroptosis, while TNBC cell lines exhibit variable features of cell death pathways." (PMID 41596270, 2026). "This study reveals that OpA induces typical pyroptosis-like characteristics, including cellular swelling, plasma membrane rupture, GSDMD cleavage, and release of cytokines in breast cancer cells." (PMID 41596270, 2026). "GSDMD represents a promising therapeutic target for mitigating the metastatic progression of breast cancer to the lung." (PMID 40324993, 2025). "The expression analysis of caspase-1, GSDMD, and IL-1β in 108 cases of breast cancer by means of immunohistochemistry method demonstrated that the components are positively correlated with each other." (PMID 41291696, 2025). "In this study, GSDMD was significantly increased in lung neutrophils at the metastatic stage from a murine orthotropic 4T1 breast cancer model." (PMID 40324993, 2025). "DHA 1 is a conjugated polyene fatty acid that has demonstrated its pyroptotic action on breast cancer cells through caspase-1/GSDMD activation." (PMID 39316325, 2025). "And HIC1 was positively associated with GSDMD across multiple cancer types, including bladder cancer (BLCA), breast cancer (BRCA), lung squamous cell carcinoma (LUSC), pancreatic cancer (PAAD), and colon cancer (PARD)." (PMID 40279559, 2025).
breast cancer (continued). "Another study indicated that nanoparticle-delivered active GSDMD sensitized mammary tumors to anti-PD1 therapy and pyroptosis of less than 15% of tumor cells was sufficient to clear entire tumor grafts by anti-PD1 therapy." (PMID 40701951, 2025). "We discovered that SNRPE targeting enhanced ROS generation and induced caspase-1/GSDMD-mediated pyroptosis in mammary carcinoma cells." (PMID 40386046, 2025). "In order to confirm the expression of GSDMD at the protein level in breast cancer, we stained breast cancer samples for GSDMD by immunohistochemistry." (PMID 39224600, 2024). "This supports previous observations in a cohort of 108 patients with breast cancer, in which higher intratumoral protein levels of GSDMD correlated with lower pathological grade, smaller tumor size and lower TNM classification stage." (PMID 39224600, 2024). "In breast cancer, we found that when comparing mRNA expression of GSDMD in the top 25% vs. bottom 25% GSDMD-expressing patients, high expression of GSDMD correlated with improved survival." (PMID 39224600, 2024). "In breast cancer, we observed that GSDMD was expressed both in cancer cells and in the microenvironment, including endothelial cells, fibroblasts and most immune cell types, such as myeloid cells and B and T lymphocytes." (PMID 39224600, 2024). "Research has indicated that GSDMD is highly expressed in breast cancer patients with a HER2-positive status, correlating with diminished response to breast cancer chemotherapy and poorer prognosis." (PMID 38001342, 2024). "To determine which cell types expressed GSDMD, we used publicly available human single-cell RNA data sets from human breast cancer (n=84) and liver cancer (n=21)." (PMID 39224600, 2024). "Here we show that in human breast cancer and hepatocellular carcinoma, GSDMD is expressed in many immune cell subtypes and in tumor cells." (PMID 39224600, 2024). "For example, cisplatin has been demonstrated to be involved in NLRP3/caspase-1/GSDMD pyroptosis pathway in breast cancer cells." (PMID 36932407, 2023). "RIG-I agonists can activate the intrinsic immune effector RIG-I in breast cancer cells, increase the immunogenicity of the tumor, activate caspase-1 cleavage of GSDMD in vitro, and are a viable approach for the treatment of breast cancer." (PMID 37542283, 2023). "Taxol and cisplatin were shown to induce pyroptosis through the GSDMD/caspase-1 pathway in nasopharyngeal carcinoma and breast cancer, respectively." (PMID 38007535, 2023). "It has been reported that cleavage of GSDMD can switch apoptosis to pyroptosis, which promotes the function of lymphocytes in breast cancer cells, facilitates tumor necrosis, and predicts poor prognosis in patients." (PMID 36161280, 2023). "Docosahexaenoic acid triggers caspase-1 activation, GSDMD maturation, and IL-1β secretion in breast cancer cell line, MDA-MB-231, through lysosomal damage and ROS formation." (PMID 36932407, 2023). "The expression level of GSDMD in breast cancers was significantly lower than that in neighboring normal tissues." (PMID 36823153, 2023). "Cisplatin induced anti-breast cancer effects at least partly by activating MEG3/NLRP3/caspase-1/GSDMD pathway." (PMID 36936274, 2022). "We found that, for a variety of tumours, including breast cancer, patients with high expression of GSDMD had a better response to chemotherapy regimens containing platinum drugs than patients with low expression." (PMID 35289335, 2022). "The expression of GSDMD was evidently different between 108 cases of breast cancer tissues and 23 cases of para-cancerous benign tissues." (PMID 33634141, 2021). "The clinical utility of GSDMD as a prognostic factor and a genuine therapeutic target for breast cancer should be adequately investigated in future studies." (PMID 33634141, 2021). "The levels of pyroptosis signaling pathway effectors caspase-1, IL-1beta, and GSDMD involve in the invasion and metastasis of breast cancer." (PMID 34381023, 2021).
breast cancer (continued). "The GSDMD expression level was inversely correlated with the clinical stage, the pathologic grade of tumor tissues, tumor size and metastasis in patients with breast cancer." (PMID 33634141, 2021). "Our research has demonstrated that OpA triggers the formation of membrane pores and the uptake of Sytox Green, indicating the induction of lytic cell death in breast cancer cells, including activation of GSDMD in HER2-positive SKBR3 cells or via an undetermined mechanism in TNBC cells." (PMID 41596270, 2026). "Also, nobiletin 59, a methoxy flavone, has pyroptotic induction efficacy against breast cancer through caspase-1/GSDMD/NLRP3 activation." (PMID 39316325, 2025). "Additionally, docosahexaenoic acid (DHA) has been proven to trigger MDA-MB-231 breast cancer cell pyroptosis via the caspase-1/GSDMD pathway, inducing IL-1β secretion, translocation of HMGB1 to the cytoplasm, and pore formation in the cell membrane." (PMID 38016064, 2023). "In addition, breast cancer patients with high expression of GSDMD have lower tumor clinical stage and histological grade." (PMID 36823153, 2023). "As for GSDMD, intensive studies on the modulation and mechanisms of the GSDMD are needed to deepen our understanding of GSDMD-mediated breast cancer and to develop GSDMD-targeting strategies that could specifically activate the pyroptosis." (PMID 36119049, 2022). "For example, via caspase-1-dependent activation of proIL-1β and regulation of IL-1 secretion by GSDMD, inflammasomes support development of lung, gastric and mammary cancer, most likely through induction of inflammation and angiogenesis as well as suppression of anti-tumor immunity by IL-1β." (PMID 36581625, 2022). "This also means that proteins like caspase-1, IL-1β and GSDMD may affect the development and prognosis of breast cancer, providing new molecular targets for the clinically targeted treatment of breast cancer." (PMID 34381721, 2021). "Since caspase-1 mediates pyroptosis cell death by triggering gasdermin D activation, we analyzed if DHA could trigger gasdermin D cleavage in breast cancer cells MDA-MB-231." (PMID 29386662, 2018). "We confirm this hypothesis by showing the expression of the gasdermin D N-terminal fragment (31 kDa) induced in MDA-MB-231 breast cancer cells treated with DHA." (PMID 29386662, 2018). "In summary, although GSDMD expression was associated with survival and a decreased M2-type macrophage signature in patients with breast cancer, we did not observe a major impact of GSDMD deficiency in two different mouse cancer models, of which one is known to be IL-1β-dependent." (PMID 39224600, 2024). "Likewise, the higher expression of GSDMD was related to better prognosis in breast cancer patients." (PMID 36823153, 2023). "They found that cisplatin could induce MDA-MB-231 cell pyroptosis via upregulating the lnc RNA MEG3 and activating the NLRP3/caspase-1/GSDMD pathway, which would accelerate the inflammatory cytokines (IL-18 or IL-1β) release and effectively treat breast cancer." (PMID 38016064, 2023). "Meanwhile, breast cancer pathological grade and TNM staging were adversely connected with the levels of pyroptosis-associated proteins expression, which concludes that the occurrence, growth, metastasis, and prognosis of breast cancer are significantly influenced by GSDMD." (PMID 36119049, 2022). "GSDMD was significantly upregulated in Bladder Urothelial Carcinoma (BLCA), Breast Cancer (BRCA), and other tumors, while it was notably downregulated in Colon Adenocarcinoma (COAD), Kidney Chromosome (KICH), and several others." (PMID 40491921, 2025). "Despite their important roles in specific types of lytic cell death, at least in these unstratified breast cancer patients, NINJ1, GSDMD and MLKL showed much lower correlation with overall response to chemotherapy." (PMID 41225536, 2025).
breast cancer (continued). "The positive or negative association of elevated GSDMD expression with survival differs according to the tumor type studied: in urothelial carcinoma and melanoma, high GSDMD expression was found to correlate with an increase in overall survival, as observed for breast cancer in this study." (PMID 39224600, 2024). "In breast cancer, hypoxia-induced upregulation of intracellular and extracellular gp96, which induces CD8+ T cell pyroptosis through the GSDMD-dependent pathway and facilitates immune evasion." (PMID 36823153, 2023). "Docosahexaenoic acid (DHA) inhibits breast cancer, and when it is added to the breast cancer cell line MDA-MB-231, caspase-1 and GSDMD activities are enhanced, and pyroptosis occurs, which manifests as increased IL-1β secretion and membrane perforation." (PMID 36605484, 2023). "Surprisingly, we found a widespread amplification and overexpression of the protein-coding genes between the GSDMD and HSF1 in breast cancer." (PMID 36497066, 2022). "The results showed the expression and distribution of GPX4, GSDMD, GSDMC, IL18 in breast cancer and normal tissues." (PMID 36138348, 2022). "Then, after being exposed to DHA, breast cancer cells secreted more IL-1β and moved HMGB1 from the nucleus to the cytoplasm via activating caspase-1 and GSDMD." (PMID 36119049, 2022). "It showed a low mRNA expression trend of GPX4, GSDMD and GSDMC in all three types of breast cancer cells, while the mRNA expression of IL18 varied." (PMID 36138348, 2022). "GSDMD and GSDME, two essential pyroptosis substrates, play significant roles in the etiology and pathogenesis of breast cancer." (PMID 36119049, 2022). "added DHA to breast cancer cells MDA-MB-231 and found that the activity of caspase-1 and GSDMD were enhanced, the secretion of IL-1β was increased, and showed pore-formation activity, which suggesting the occurrence of pyroptosis." (PMID 34381721, 2021). "Also, numidargistat 25 is reported as a pyroptotic agent against breast cancer and various other cancers by activating GSDME, caspase-1, and caspase-3/GSDMD." (PMID 39316325, 2025). "In contrast to the findings in breast cancer, we found that enhanced expression of GSDMD in patients with hepatocellular carcinoma (HCC) did not correlate with improved overall survival, relapse-free survival or with a myeloid signature." (PMID 39224600, 2024). "The expression of GSDMD, a key effector of pyroptosis, was evaluated in MCF-7 and MDA-MB-231 breast cancer cell lines following transfection with GFPT1-targeting siRNA (siRNA-GFPT1#3), an empty vector control (PcDNA3.1), and a GFPT1 overexpression vector (PcDNA3.1 (+)/GFPT1)." (PMID 39664728, 2024). "To assess the impact of GSDMD in the tumor microenvironment rather than tumor cell-intrinsic GSDMD, we implanted EO771 breast cancer cells into the mammary fat pads of GSDMD-deficient mice." (PMID 39224600, 2024). "GSDMD and AMPK may be proposed as new markers for biomarker-based subtyping and new targets for medical intervention in breast cancer." (PMID 37495617, 2023). "Several studies have shown that the pyroptosis core genes behave differently in different tumors, with GSDMC, GSDMD, and GSDMB acting as oncogenes in colorectal cancer, small-cell lung cancer, and breast cancer, respectively, while GSDME acts as a tumor suppressor in a variety of cancers." (PMID 35769504, 2022). "Because of the substantial co-overexpression of GSDMD and HSF1 in breast cancer, this serendipity observation allowed us to postulate that the genes residing in between the GSDMD and HSF1 loci might also be upregulated in breast cancer." (PMID 36497066, 2022). "To test this hypothesis, we examined the expression of the genes residing in between the GSDMD and HSF1 in multiple breast cancer genomic datasets in the case of breast cancer (METABRIC) and breast invasive carcinoma (TCGA, Firehose Legacy)." (PMID 36497066, 2022).
breast cancer (continued). "In vivo, anti-tumor immunity could be stimulated through GSDME activation 20, suggesting an advanced anti-tumor potential of GSDMD and GSDME in breast cancer." (PMID 35541900, 2022). "To verify which Gasdermin protein could be involved in drug pyroptosis‐induced in breast cancer cells, we assessed the protein expression of GSDME and GSDMD by Western blotting." (PMID 34369076, 2021). "In summary, the deficiency in GSDMD did not exert an impact on tumor growth, immune cell infiltration, or the immune landscape in either the EO771 breast cancer or the Hepa1-6 hepatoma model, although intratumoral Cxcl10 levels were elevated in Hepa1-6 tumors grown in Gsdmd-/- mice." (PMID 39224600, 2024). "The level of GSDME expression varies by the type of breast cancer which manifest it could be a novel premonitory marker in breast cancer while GSDMD expression is not clear fully." (PMID 36119049, 2022). "Moreover, MEG3 was found to promote cisplatin-induced pyroptosis by promoting the NLRP3/caspase-1/GSDMD axis, implying that MEG3 may be an effective therapeutic target for enhancing breast cancer chemotherapy." (PMID 35392086, 2022). "In addition, MEG3 was found to activate cisplatin-induced cellular pyroptosis by promoting NLRP3/caspase-1/GSDMD axis, implying that MEG3 could be effective therapeutic target of breast cancer." (PMID 34488540, 2021). "However, expression of GSDMD was not correlated with breast cancer subtypes." (PMID 33558527, 2021).